CXCL11 (C-X-C motif chemokine ligand 11)
Diseases named in the same sentence as CXCL11 in open-access papers (continued):
Sharing a sentence is not in itself a finding about the gene and the disease.
malaria (8 papers, 2009 to 2025). Malaria is a serious and sometimes fatal disease caused by a parasite that commonly infects a certain type of mosquito which feeds on humans. "Again, studies have indicated that the concentration of CXCL11 was greater in symptomatic than asymptomatic malaria and was upregulated among the fever-positive groups, which identified CXCL11 as a possible biomarker for malarial fever." (PMID 36239109, 2022). "Relative involvement of CXCL10 and CXCL11 has been found to recruit inflammatory leukocytes of malaria-infected mice." (PMID 36239109, 2022). "Distinct cytokine profiles in malaria and HIV coinfections compared to malaria monoinfections were increased IL-12, CXCL9, CXCL11, IL-18, and G-CSF levels and decreased TNF and IL-4 levels." (PMID 36716305, 2023). "They demonstrated that malaria and L. loa co-infections had decreased levels of C-X-C motif chemokine 5 (CXCL5) and comparable levels of CX3CL1, CXCL7, CXCL9, CXCL11, and CCL28 compared with malaria monoinfection." (PMID 36269701, 2022). "Although the exact mechanism of these chemokines in malaria pathogenesis is unknown, increased levels of chemokines such as CXCL9, CXCL10, and CXCL11 have been proposed as predictive markers for HIV disease progression." (PMID 36716305, 2023). "The results show that in early malaria, selected immune response-related genes were up-regulated including α β and γ interferon-related genes, as well as genes of IL-15, CD36, chemokines (CXCL10, CCL2, S100A8/9, CXCL9, and CXCL11), TRAIL and IgG Fc receptors." (PMID 24188121, 2013).
liver cancer (7 papers, 2021 to 2024). An epithelial or non-epithelial malignant neoplasm that arises from the liver. "Another aspect, the CXCL11, a cytokine involved in the recruitment of activated T cells to inflammatory sites, was found significantly affect the stemness genes, sphere formation, and tumorigenicity in liver cancer." (PMID 36785674, 2023). "Additionally, CXCL11 expression was also upregulated in liver cirrhosis or liver cancer tissues, compared to normal liver tissues, within the GSE14323 and GSE6764 datasets." (PMID 33707417, 2021). "Among those, CXCL5, CXCL9, CXCL10, and CXCL11 were significantly elevated in patients with early HCC according to the Barcelona Clinic Liver Cancer (BCLC) stages 0/A compared to cirrhotic controls without HCC." (PMID 36982370, 2023).
multiple sclerosis (7 papers, 2019 to 2024). A progressive autoimmune disorder affecting the central nervous system resulting in demyelination. "Interestingly, we found that upon direct contact with Th17-polarized cells, OLs significantly upregulate their expression of chemokines CXCL10 and CXCL11, whose levels in the CSF are associated with clinical evolution in multiple sclerosis." (PMID 35479072, 2022). "CxCl11 brain levels increase in response to trauma and in neurological diseases, such as multiple sclerosis and neuroborreliosis." (PMID 36550567, 2022). "Recent evidence has also indicated that serum expression of CXCL10 and CXCL11 is increased in multiple sclerosis patients and may be involved in disease pathogenesis." (PMID 33806460, 2021). "CXCR3 is abundantly expressed on CNS-infiltrating T cells in multiple sclerosis patients and coordinates CNS-directed T cell migration in response to its three ligands, CXCL9/CXCL10/CXCL11." (PMID 38349430, 2024). "Previous studies have shown that CXCL11/CXCR3 expression is significantly upregulated in many CNS diseases, such as cerebral ischemic stroke and multiple sclerosis." (PMID 39315097, 2024).
rheumatoid arthritis (7 papers, 2008 to 2025). A chronic, systemic autoimmune disorder characterized by inflammation in the synovial membranes and articular surfaces. "CXCL11 was upregulated in rheumatoid arthritis, with the manifestation of exacerbated inflammatory injury and limited cell activity." (PMID 36243708, 2022). "Lastly, ruxolitinib inhibited the expression of CXC10 and CXCL11 by MDMs from healthy subjects and by macrophages isolated from the synovial fluid of patients with rheumatoid arthritis." (PMID 36059986, 2022). "Additionally, CXCL11 ablation reduced cartilage degradation and inflammatory injury in LPS-induced rheumatoid arthritis." (PMID 36243708, 2022). "Serum samples from 49 patients diagnosed with pSS, 33 patients with rheumatoid arthritis (RA), and 30 healthy controls (HCs) were collected for measurements of CXCL9, CXCL10, CXCL11, and CXCR3." (PMID 38900301, 2024). "TNFα, IL-1β, and hypoxia also up-regulate the expression of cytokines, including IL-6, CXCL8 (namely, IL-8), CCL2, CXCL11, CXCL12, and VEGF, as well as the expression of cytokine receptors such as TNFRSF9 in synovial fibroblasts derived from rheumatoid arthritis (RA) patients." (PMID 35967331, 2022).
sarcoidosis (7 papers, 2010 to 2024). Sarcoidosis is a multisystemic disorder of unknown cause characterized by the formation of immune granulomas in involved organs. "When comparing to control subjects, the expression levels of CC chemokines CCL3 (P = 0.043), CCL4 (P = 0.034), CCL5 (P < 0.001), and CCL8 (P = 0.031) and CXC chemokines CXCL9 (P < 0.001), CXCL10 (P = 0.002), and CXCL11 (P = 0.008) were found to be elevated in sarcoidosis patients." (PMID 26696750, 2015). "For example, CD103+CD4+ T-cells in BALF of sarcoidosis patients are lower than in other ILD, while some chemokines able to recruit T-helper lymphocytes, such as CXCL9, CXCL10, and CXCL11, are increased." (PMID 39062076, 2024). "In contrast to our negative findings regarding macrophage polarization, previous studies have demonstrated higher expression of the M1 markers CXCL10, CXCL11 and CXCL16 in sarcoidosis patients compared to healthy subjects." (PMID 20813038, 2010). "Increase in CXCR3 CD226 CD4 in sarcoidosis • CXCL9 and CXCL11 are ligands of CXCR3, are IFN-inducible and found in granulomas.• CXCR3 expressing CD4+ T cells are recruited in granuloma.B cells: more prevalent in the BAL of sarcoidosis and CTD-ILD patients compared to IPF." (PMID 39896815, 2024). "Enriched genes including MPO (myeloperoxidase), CXCL11, IL1A, CXCL10, FCGR3B, IL1B, TTN (titin), BATF2, VIP (vasoactive intestinal peptide), TLR3, CCR2, TLR7, and CR1 wereclosely related to sarcoidosis." (PMID 38137330, 2023). "It has been reported that alveolar macrophages from sarcoidosis patients secreted large amounts of CXCR3 ligands, including CXCL9, CXCL10, and CXCL11, that could play crucial roles in the accumulation of Tregs in the site of inflammation." (PMID 37189479, 2023).
vitiligo (7 papers, 2015 to 2025). Generalized well circumscribed patches of leukoderma that are generally distributed over symmetric body locations and is due to autoimmune destruction of melanocytes. "Plasma IFN-γ, CXCL9, CXCL10, CXCL11 and IL-6 might be potential biomarkers for vitiligo recurrence, with CXCL9 also associated with disease activity." (PMID 39981245, 2025). "In conclusion, this study discovers that plasma IFN-γ, IFN-γ-regulated chemokines, including CXCL9, CXCL10 and CXCL11, and IL-6 might be potential biomarkers for vitiligo recurrence, with CXCL9 also associated with disease activity." (PMID 39981245, 2025). "Correlation analysis showed a positive relationship between IFN-γ, CXCL9, CXCL10, CXCL11, IL-6, and IL-15 in the plasma of patients with recurrent vitiligo." (PMID 39981245, 2025). "Then, ROC curve analysis for IFN-γ, CXCL9, CXCL10, CXCL11 and IL-6 in recurrent versus persistent stable vitiligo were conducted." (PMID 39981245, 2025). "In vitiligo, CXCL11 has little data including 4 studies with in total of 62 vitiligo patients and 67 controls." (PMID 36911664, 2023). "Treatment with CXCL9 and CXCL11 also induced a significant melanocyte death in both healthy (P = 0.034 and P = 0.007, respectively) and vitiligo (P = P < 0.001 and P = 0.01) melanocytes that was almost completely prevented by the use of SiCXCR3B." (PMID 31097717, 2019). "Additionally, IFN-γ, CXCL9, CXCL11, and IL-6 also exhibit substantial individual predictive capabilities for vitiligo recurrence, with AUC values of 0.806, 0.773, 0.785, and 0.709, respectively." (PMID 39981245, 2025). "Our results showed that, except for IL-15, the levels of these factors were significantly higher in recurrent patients compared to persistent stable patients, which suggest that increased levels of IFN-γ, CXCL9, CXCL10, CXCL11 and IL-6 are potential triggers for vitiligo recurrence." (PMID 39981245, 2025). "The relationship between the expression of CXCL11 and vitiligo remains unclear because of the limited research on CXCL11 and vitiligo." (PMID 39981245, 2025). "Based on previous research, we propose a hypothesis that IFN-γ, CXCL9, CXCL10, CXCL11, IL-6, and IL-15 are involved in the recurrence of vitiligo and are interconnected." (PMID 39981245, 2025). "Therefore, we would expect to detect a majority of chemokines (e.g. CXCL10, CXCL11) and cytokines (e.g. IL-17, IL-23) being differentially expressed across the different publications when comparing vitiligo patients to healthy controls or active vs stable vitiligo patients." (PMID 38715599, 2024). "These include CXCL9, CXCL10, and CXCL11 and its receptor CXCR3, both in peripheral cells of the immune system and in the skin of patients diagnosed with vitiligo." (PMID 32992956, 2020). "Stimulation of healthy or vitiligo melanocytes with IFNγ induced a significant increase in mRNA expression of CXCL4, CXCL9, CXCL10 and CXCL11." (PMID 31097717, 2019). "The difference was even more pronounced with CXCL11, that induced much lower cell death compared to CXCL10 (P < 0.001 for both healthy and vitiligo)." (PMID 31097717, 2019). "IFN-γ, CXCL9, CXCL10, CXCL11, IL-6, and IL-15 were expressed at higher levels in the circulation of patients with both segmental and non-segmental vitiligo compared to healthy controls (p < 0.001)." (PMID 39981245, 2025). "CXCL11 is elevated in the lesion compared to non-lesion skin of vitiligo (V-L:21.83 ± 22.65pg/ml; V-NL: 12.85 ± 7.763 pg/ml, p = 0.027)." (PMID 35464413, 2022). "However, addition of pre-stressed NKs or ILCs from vitiligo patients dramatically increased their own melanocyte production of CXCL9, CXCL10, CXCL11 and IFNγ." (PMID 31097717, 2019). "Two studies found no clearly increased mRNA CXCL11 levels in vitiligo skin, while one study did." (PMID 36911664, 2023).
Cirrhosis (6 papers, 2016 to 2023). A chronic disorder of the liver in which liver tissue becomes scarred and is partially replaced by regenerative nodules and fibrotic tissue resulting in loss of liver function. "In addition, CXCL9, CXCL10, and CXCL11 are related to the migration of TRAIL CD56+bright NK cells that promote liver injury to the liver in chronic hepatitis B-associated cirrhosis." (PMID 36504808, 2022). "In this context, two recent studies have investigated the role of CXCL9 and CXCL11 in patients with cirrhosis receiving TIPS." (PMID 27578545, 2016). "Similarly, CXCL11 and CXCL9 were only marginally significant after FDR correction in logistic regression analyses but were both identified as differentiating markers of cirrhosis in CDA analyses." (PMID 34782638, 2021). "Patients with CXCL10 rs3921 CG or CXCL11 rs4619915 AG genotypes had lower odds of significant fibrosis (LSM ≥ 7.1 kPa) [adjusted OR (aOR) = 0.56 (p = 0.008)], advanced fibrosis (LSM ≥ 9.5 kPa) [aOR = 0.55 (p = 0.013)], and cirrhosis (LSM ≥ 12.5 kPa) [aOR = 0.57 (p = 0.051)]." (PMID 28755163, 2017). "Furthermore, patients with CXCL10 rs3921 CG or CXCL11 rs4619915 AG genotypes had lower odds of significant fibrosis (LSM ≥ 7.1 kPa) [adjusted OR (aOR) = 0.56 (p = 0.008)], advanced fibrosis (LSM ≥ 9.5 kPa) [aOR = 0.55 (p = 0.013)], and cirrhosis (LSM ≥ 12.5 kPa) [aOR = 0.57 (p = 0.051)]." (PMID 28755163, 2017).
diabetes (6 papers, 2011 to 2024). "In addition, higher levels of the cytokine receptors, sIL-6R and sTNFR1, and the chemokines, CCL19, CCL20, CCL21, and CXCL11, were also associated with a history of self-reported diabetes at the <10% level." (PMID 28753646, 2017). "We observed associations between self-reported diabetes and the chemokines previously reported in the literature, including CXCL10 and interleukin-8 (IL-8), as well as identified a number of novel associations such as: CCL19, CCL20, CCL21, CXCL6, and CXCL11." (PMID 28753646, 2017). "Factors associated with the absence of collaterals were the cytokine profile consisting of CXCL11 (p = 0.002) and IFN-γ (p = 0.021), and the clinical factors of hypertension (p = 0.007), and diabetes (p = 0.004)." (PMID 21731663, 2011). "In addition to CXCL10 and CXCL11, our analysis of serum chemokines and cytokines revealed elevated concentrations of BAFF in individuals with long-standing diabetes." (PMID 29881878, 2018). "Although the changes in CXCR3 expression were only significant in one of the newly diagnosed cohorts, they showed the same downward trend that we observed in the long-standing diabetes cohorts, along with the same significant increases in serum levels of CXCL10 and CXCL11." (PMID 29881878, 2018). "In people without diabetes SRA1 expression was associated with CCL3 (r = 0.298, p = 0.036), CCL8 (r = 0.344, p = 0.021), CXCL11 (r = 0.400, p = 0.003), TNF-α (r = 0.317, p = 0.030), TGF-β (r = 0.514, p < 0.0001), IL13 (r = 0.310, p = 0.028), and IL18 (r = 0.547, p < 0.0001)." (PMID 34685582, 2021).
HIV-1 infection (6 papers, 2018 to 2023). The type species of lentivirus and the etiologic agent of acquired immunodeficiency syndrome (AIDS). "We identified a cluster of IRPs (cluster 7), including CXCL11, CXCL9, TNF, CXCL10, and IL18, which was closely associated with T cell dysregulation during chronic HIV-1 infection." (PMID 36408648, 2023). "A previous study demonstrated that CXCL9, CXCL10, and CXCL11 levels can predict HIV-1 disease progression during primary HIV-1 infection." (PMID 36408648, 2023). "A panel of plasma CXCL9, CXCL10, and CXCL11 measured during primary HIV-1 infection could predict long-term HIV disease prognosis in an MSM group and has potential as a novel biomarker in the clinic." (PMID 31836011, 2019). "Many studies have previously reported a correlation between the observed increase in the production of pro-inflammatory cytokines IL-1β, IL-6, IL-18 and TNF-α; and IFN inducible chemokines CXCL9, CXCL10 and CXCL11 during the course of HIV-1 infection and the up regulation of HIV-1 replication." (PMID 29373606, 2018).
non-small cell lung carcinoma (6 papers, 2017 to 2023). A group of at least three distinct histological types of lung cancer, including non-small cell squamous cell carcinoma, adenocarcinoma, and large cell carcinoma. "Furthermore, CXCL11 increased CD8+ T-cell recruitment to the TME during docetaxel treatment in non-small-cell lung cancer, reducing tumor progression." (PMID 36030223, 2022). "Moreover, the activation of NF-κB can stimulate the release of CXCL11 in non-small cell lung cancer cells." (PMID 32527308, 2020). "In non-small cell lung cancer, CCL19 and CXCL11 reduced the receptor activator of nuclear factor-κB ligand/osteoprotegerin ratio, an indicator of osteoclast stimulation." (PMID 38075694, 2023). "IGF2BPs, as functional downstream modulators of circNDUFB2, regulate the secretion of CXCL10, CXCL11, CCL5, and IFNβ in non-small cell lung cancer (NSCLC)." (PMID 36225914, 2022).
cervical cancer (5 papers, 2020 to 2023). A primary or metastatic malignant neoplasm involving the cervix. "This study revealed that the presence of HPV16 and 18 oncogenes significantly alter the expression of CCL28, CXCL1, CXCL2, CXCL3, CXCL6, CXCL8, CXCL10, and CXCL11; overexpression of those chemokines was also confirmed in cervical cancer biopsies." (PMID 37893029, 2023). "As a chemotactic cytokine, CXCL11 is overexpressed in various solid tumors and promotes tumorigenesis and development, but little research has been conducted in cervical cancer." (PMID 36478746, 2022). "Overall, we have reason to believe that EphA2 promotes the development of cervical cancer through the CXCL11/PD-L1 pathway." (PMID 36478746, 2022). "Meanwhile, the GEPIA database showed that PD-L1 and CXCL11 were highly correlated in cervical cancer (p=0.0063)." (PMID 36478746, 2022). "To further study the molecular mechanism of EphA2 in cervical cancer, we explored the downstream molecules of EphA2/CXCL11." (PMID 36478746, 2022). "This study is the first to propose that EphA2 plays a role in promoting cancer through the CXCL11/PD-L1 pathway in cervical cancer, which opens up new possibilities for targeted therapy and combined therapy of cervical carcinoma." (PMID 36478746, 2022). "It is believed that EphA2 affects the tumor microenvironment by promoting the autocrine chemokine CXCL11 in cervical cancer cells and further regulates the expression of PD-L1 on the cell surface." (PMID 36478746, 2022). "Collectively, our study uncovered a possible cancer-promoting mechanism of EphA2 and proposed for the first time that EphA2 promotes the development of cervical cancer through the CXCL11/PD-L1 pathway." (PMID 36478746, 2022). "This article explores the molecular mechanism of the cancer-promoting role of EphA2 in cervical cancer, and the results show that EphA2 promotes the proliferation, invasion, and metastasis of cervical cancer through the CXCL11/PD-L1 pathway." (PMID 36478746, 2022). "Our experimental results show that EphA2 promotes the proliferation, invasion, and metastasis of cervical carcinoma through CXCL11." (PMID 36478746, 2022). "To further demonstrate that CXCL11 mediates the cancer-promoting effect of EphA2 in cervical carcinoma, we analyzed the effect of CXCL11 on the proliferation ability of the sh-EphA2-SiHa cell line by the CCK8 assay." (PMID 36478746, 2022). "Our study demonstrated that EphA2 plays a tumor-promoting role in cervical carcinoma through the CXCL11/PD-L1 pathway, providing new guidance for the targeted therapy and combination therapy of cervical carcinoma." (PMID 36478746, 2022). "Our findings not only demonstrate the promoting effect of CXCL11 on the proliferation, invasion, and metastasis of cervical carcinoma but also the mediation of CXCL11 on the cancer-promoting effect of EphA2." (PMID 36478746, 2022). "The results of the transwell migration and invasion assay and the wound healing assay together demonstrated that the addition of CXCL11 rescued the inhibition of cervical carcinoma cell migration and invasion by the EphA2 knockout." (PMID 36478746, 2022). "The experimental results indicated that EphA2 may play a role in promoting cancer through CXCL11 in cervical cancer." (PMID 36478746, 2022). "In cervical cancer cells, CXCL11 was highly expressed when EphA2 was highly expressed." (PMID 36478746, 2022). "Data from the CCK8 assay demonstrated that the knockdown of EphA2 led to the weakening of the proliferative capacity of cervical cancer cells, whereas the replenishment of CXCL11 leads to a significant recovery of the proliferative capacity of sh-EphA2-SiHa cells." (PMID 36478746, 2022). "Therefore, we speculate that there is a signal transduction pathway of EphA2/CXCL11/PD-L1 in cervical cancer." (PMID 36478746, 2022).
cervical cancer (continued). "Moreover, it has been reported in the literature that tumor cells affect the expression of PD-L1 in cells by autocrine CXCL11, so we have reason to believe that EphA2 upregulates PD-L1 through autocrine chemokine CXCL11, thereby promoting the occurrence and development of cervical carcinoma." (PMID 36478746, 2022).